PTH (parathyroid hormone)
Diseases named in the same sentence as PTH in open-access papers (continued):
Sharing a sentence is not in itself a finding about the gene and the disease.
Kidney Disease (continued). "Thus, based on our results, we could infer that the restored levels of vitamin D acted on the PTH-vitamin D-FGF-23 axis, retarding renal disease progression." (PMID 33869246, 2021). "Moreover, the best method for the measurement of PTH in CKD patients still remains a challenging issue also in human medicine, even if the Kidney Disease: Improving Global Outcomes guidelines (2017) suggest the use of a second-generation assay, as the investigated method." (PMID 33348538, 2020). "The National Kidney Foundation Kidney Disease Outcomes Qualities Initiative’s (KDOQI) clinical guidelines for CKD state that dietary phosphorus should be restricted to 800 to 1000 mg/day for CKD patients based on stage of disease and presence of elevated serum phosphate or parathyroid hormone (PTH)." (PMID 30249044, 2018). "However, it should be noted that during the study enrollment, the Kidney Disease Improving Global Outcomes (KDIGO) guidelines were issued, thereby expanding the PTH range (150–300 pg/mL) to “approximately two to nine times the upper normal limit for the assay”." (PMID 28956807, 2017). "The scores of kidney disease component summary (KDCS), physical component summary, mental component summary, and total quality of life were significantly higher in the lower quartile of corrected serum calcium and higher quartile of serum parathyroid hormone (PTH) levels (P < 0.05)." (PMID 24719817, 2014). "Initially we questioned whether patients with tests for PTH and phosphorus had more advanced renal disease than our second cohort of 792 patients without such testing." (PMID 22133421, 2011). "In stages I and II of kidney disease, i.e. when GFR is normal or only slightly reduced, the levels of calcium, phosphate and PTH in plasma are usually not different from healthy individuals." (PMID 18266955, 2008).
cardiovascular disease (122 papers, 2010 to 2026). "Close attention should be paid to PTH control to reduce the risk of cardiovascular disease and death." (PMID 38482569, 2024). "It is known that elevated parathyroid hormone (PTH) levels are associated with various cardiovascular diseases (CVD)." (PMID 38530609, 2024). "While we found a correlation to all-cause mortality, it is worth noting that the incidence of cardiovascular disease was higher in the groups with elevated PTH levels and highest in the group with elevated levels of PTH and high levels of IGFBP-1 (60%)." (PMID 39592711, 2024). "An interplay between PTH and aldosterone can increase cardiovascular risk and can adversely affect the various cardiovascular diseases." (PMID 36389124, 2022). "Patients with cardiovascular disease are also more prone to PTH excess and have a higher risk of secondary cardiovascular events." (PMID 36142295, 2022). "A meta-analysis concerning the association between serum PTH levels and cardiovascular diseases (CVD) found that a high level of PTH is associated with an enhanced risk for overall CVD events." (PMID 35409134, 2022). "Several studies tried to evaluate the calcium, phosphate and PTH concentrations in dialysis populations and analyzed the associations from abnormal mineral metabolism to cardiovascular disease." (PMID 34202416, 2021). "The bidirectional interplay between aldosterone and PTH leads to an increased risk of developing metabolic and cardiovascular diseases." (PMID 31068134, 2019). "According to studies, also abnormalities of calcium, phosphorus, vitamin D, and parathyroid hormone (PTH) are associated with the occurrence of cardiovascular disease." (PMID 29865146, 2018). "Levels of parathyroid hormone (PTH) are mainly used to grade the extent of sHPT and both high and low PTH have been associated with cardiovascular disease (CVD) in patients on maintenance dialysis." (PMID 29478201, 2018). "It has been argued that PTH confers a risk for cardiovascular disease even at normal or slightly elevated levels and in the absence of mineral metabolism disorders." (PMID 28115793, 2017). "A recent meta-analysis indicated that higher PTH levels were associated with nearly 50% increased risk of cardiovascular disease events." (PMID 26010883, 2015). "As with the reported association between PTH and cardiovascular mortality, we find that higher-normal PTH is associated with greater albuminuria independently of all traditional risk factors and previous history of cardiovascular disease." (PMID 24505486, 2014). "The strength of our study is that it is the largest study of the association between P, cCa, and intact PTH levels, and each individual cardiovascular disease." (PMID 25494334, 2014). "We also measured serum FGF-23 levels as this bone-derived hormone is a mediator of renal phosphate wasting and stimulated by vitamin D and PTH and has also been linked to cardiovascular disease." (PMID 23029197, 2012). "Besides, PTH also serves as a significant risk factor for increased incidence of cardiovascular disease and overall mortality among CKD patients." (PMID 39829956, 2024). "We hypothesize that a bioactive PTH-associated agent may be a promising approach to regulating SOST in kidney-related diseases to reduce the risk of cardiovascular diseases or relevant mortality." (PMID 38393416, 2024). "PTH can also raise blood pressure in five ways, thus increasing the risk of cardiovascular disease." (PMID 32973674, 2020). "Therefore, reference to the rhythmic secretion of RAAS and PTH has important diagnostic and therapeutic values for cardiovascular diseases or endocrine diseases in humans and animals." (PMID 32973674, 2020). "High PTH, as well as low serum 25OHD levels, is associated with cardiovascular diseases." (PMID 30321335, 2019). "Although several explanations for the relationships between serum vitamin D, PTH, and cardiovascular disease have been presented, the underlying mechanisms remain unclear." (PMID 29088221, 2017).
cardiovascular disease (continued). "Numerous observational studies have reported an association between elevated PTH levels and cardiovascular disease, which may be due to an interaction between PTH and calcium regulation and the RAAS." (PMID 28808443, 2017). "Prolonged elevation of PTH levels may result in bone loss, fractures, cardiovascular disease, and increased mortality." (PMID 25514572, 2014). "Additional research should examine whether 25(OH)D, calcium and PTH are independently associated with cardiovascular disease and its risk factors in prospective studies." (PMID 21085485, 2010). "Lower levels of 25(OH)D and higher levels of calcium and PTH appear to be associated with different cardiovascular risk factors and may therefore affect cardiovascular disease risk through different mechanisms." (PMID 21085485, 2010). "Lower levels of 25-hydroxyvitamin D (25(OH)D, and higher levels of parathyroid hormone (PTH) and calcium have been associated with increased risk of cardiovascular disease events in prospective cohort studies, but the mechanisms underlying these associations are unclear." (PMID 21085485, 2010). "The benefits of active vitamin D analogs for reducing serum PTH levels are counterweighted by the risk of rising serum calcium levels and subsequently calcium-phosphate product, eventually leading to extraskeletal calcifications and worsening of cardiovascular disease." (PMID 34458210, 2021). "Indeed, PTH has been lately considered a mediator for bone-renal-vascular interactions and a novel causative factor for the development of cardiovascular disorders, including hypertension, left ventricular hypertrophy, congestive heart failure (HF), and both fatal and nonfatal cardiovascular events." (PMID 30662585, 2018). "Elevated PTH has been associated with increased aortic pulse pressure and impaired endothelial function, which could partially explain the relationship between PTH and cardiovascular disease." (PMID 28272298, 2017). "Though the experimental and clinical data suggest an association between NT-proBNP and PTH levels and support their role as predictors of clinical outcomes in adult with cardiovascular diseases, any significant association could be detected between NT-proBNP and PTH levels in young CHD patients." (PMID 26955207, 2016). "The other most important patient features included markers reflective of bone metabolism (PTH, vitamin D levels) and cardiovascular disease (presence of either one of CAD, MI, AF)." (PMID 39746010, 2025). "The oral frailty group was significantly older and had slower gait speed, fewer teeth, higher intact parathyroid hormone, higher C-reactive protein, higher frequency of cardiovascular disease, and lower employment at baseline." (PMID 40573061, 2025). "Across all models, the 5 comorbidities most consistently with the greatest influence on mortality prediction were: CKD, advanced age (>80 years), elevated PTH (>6.8pmol/L), cardiovascular disease (CAD, MI, AF or HTN) and PRCF residence." (PMID 39746010, 2025). "Patients who died were significantly older (p < 0.001), had more cardiovascular disease (p = 0.010), had central venous catheter at the start of HD (p < 0.001), lower parathyroid hormone (PTH) level (p = 0.014) and higher CAR (p = 0.015)." (PMID 36995004, 2023). "High FGF-23 blood levels have been found to be correlated positively with dialysis vintage and parathyroid hormone (PTH) and were found to be associated with cardiovascular disease in hemodialysis patients." (PMID 36970967, 2023). "Our research holds significant clinical value, particularly for individuals with significantly elevated PTH levels in patients with cardiovascular diseases or CKDs." (PMID 37842376, 2023). "Elevated serum parathyroid hormone (PTH) contributes to bone and cardiovascular disorders and has been independently associated with all-cause and cardiovascular mortality in CKD patients." (PMID 36611532, 2022).
cardiovascular disease (continued). "The role of PTH in cardiovascular diseases—and HF in particular—has been long debated, although definite data are lacking." (PMID 36286286, 2022). "Previously, PTH was found to be an important component of EndMT in CKD-induced cardiovascular disorders." (PMID 35409134, 2022). "Increasing age, the presence of cardiovascular disease and NLR ≥ 3.5 and higher PTH level were independently associated with serum albumin < 38 g/L." (PMID 36176632, 2022). "Parathyroid hormone (PTH) was considered to be an important component of EndMT in CKD‐induced cardiovascular diseases." (PMID 33945189, 2021). "The high level of parathyroid hormone (PTH) in the blood causes irreversible renal dysfunction and cardiovascular disease." (PMID 34202416, 2021). "Apoptosis of aortic smooth muscle cells can promote cardiovascular disease, but the role of parathyroid hormone (PTH) and sirtuin 1 in the pathophysiology of apoptosis is still unclear." (PMID 31106631, 2019). "Elevated PTH concentrations should also be considered beyond calcium and phosphate dysregulation when explaining cardiovascular diseases." (PMID 31068134, 2019). "PTH is the main regulator of blood calcium and phosphorus balance, and its functional impairment contributes to the development of cardiovascular disease-related pathologies." (PMID 31106631, 2019). "It is characterized by persistently increased serum parathyroid hormone (PTH) concentration and is associated with elevated mortality, cardiovascular disease and bone disease." (PMID 29449603, 2018). "In the article titled “The Role of Parathyroid Hormone and Vitamin D Serum Concentrations in Patients with Cardiovascular Diseases”, the “≤” signs should be replaced with “=” signs throughout the article." (PMID 30627221, 2018). "This review summarizes the evidence supporting the contribution of salt and aldosterone to cardiovascular disease and the possible cardiac and skeletal consequences of the mutual interplay between aldosterone, parathyroid hormone, and salt." (PMID 29056965, 2017). "Evidence has shown an increased incidence of cardiovascular disease with PTH levels in the upper quartile of normal range, demonstrating that even slight elevations in serum PTH can affect cardiovascular health." (PMID 28272298, 2017). "In this narrative review, we outline the evidence supporting the contribution of salt and aldosterone to cardiovascular disease and the possible consequences of the mutual interplay between salt, aldosterone, and PTH on cardiac and skeletal damage." (PMID 29056965, 2017). "Elevated calcium, parathyroid hormone and parathyroid hormone-like peptides provoke and promote the abnormal calcification process and cardiovascular diseases." (PMID 27276077, 2016). "The results of the present study show that higher TG/HDL-C ratios in the CKD patients are associated with increased cardiovascular disease risk as shown by the elevated ADMA, PTH, phosphate and lower FMD and eGFR levels." (PMID 25885289, 2015). "Elevated PTH has been shown to play a role in various cardiovascular disorders including abnormal vasodilation." (PMID 20169119, 2010). "Non‐completers were older, with higher cardiovascular disease rates and lower serum PTH levels." (PMID 40726317, 2025). "Although our analysis had limited cases, lower Hb levels and higher PTH levels preoperatively might reflect a serious SHPT resulting in more fatal cardiovascular disease events." (PMID 36142295, 2022). "It is very important to understand the normal physiological relationship between the RAAS and PTH because it has been previously established that dysregulation of aldosterone as well as PTH plays an important role in the development and progression of cardiovascular disease." (PMID 36389124, 2022).
cardiovascular disease (continued). "Based on the guideline-recommended by Kidney Disease: Improving Global Outcomes (KDIGO), Vitamin D Receptor Activators (VDRA) and calcimimetics are the optimal strategies of SHPT treatment, complemented to decrease PTH, prevent hypocalcemia, improve survival, and reduce cardiovascular disease." (PMID 34368073, 2021). "Adjusting for levels of uric acid did not alter the association between PTH and cardiovascular disease why this cannot explain the high risk of CVD in the lowest quartile of PTH." (PMID 29478201, 2018). "Our intention was to describe the relation between pre-transplant plasma PTH and long-term risk of incident cardiovascular disease after renal transplantation in patients with and without pre-transplant PTX." (PMID 29478201, 2018). "Excess PTH levels may at least in part promote cardiovascular disease by increasing the cardiac contractility and myocardial calcification." (PMID 25922846, 2015). "Additionally, patients treated with PTH analogues had a lower risk of cardiovascular disease compared to patients not receiving PTH analogue therapy." (PMID 40869557, 2025). "However, vitamin D is part of a system known as mineral metabolism, which encompasses several other components, such as FGF23, PTH and phosphate that may be also related to the incidence of cardiovascular disease." (PMID 35887917, 2022). "In addition, there is a lack of data linking the achievement of specific PTH levels following treatment intervention with hard outcomes (for example fracture risk and cardiovascular disease) in non-dialysis CKD." (PMID 34170509, 2021). "Secondly, PTH may promote vascular and cardiac remodeling, accelerating the development of cardiovascular disease in patients with PHPT, but this is explained by the direct effect of PTH on vascular smooth muscle cells and endothelial cells, instead of the RAAS." (PMID 32973674, 2020). "This pilot study determined serum vitamin D and parathyroid hormone (PTH) levels in a sample of participants from the University of Illinois at the Chicago Cohort of Patients, Family and Friends (UIC Cohort) and examined their association with traditional cardiovascular disease risk factors." (PMID 31434350, 2019). "We analysed other biomarkers that, in recent years, have been related to cardiovascular disease, such as suPAR, FABP4, and MM biomarkers (P, PTH, vitamin D, FGF-23, klotho)." (PMID 39940753, 2025). "The groups with elevated PTH levels had higher incidence and the group with elevated levels of PTH and high levels of IGFBP-1 had the highest incidence of cardiovascular disease." (PMID 39592711, 2024). "PTH is also known as a uremic toxin; serum levels increase as CKD progresses and have many systemic side effects, including cardiovascular disease." (PMID 39202612, 2024). "Future, large-scale observational studies, using levels of PTH after PTX to predict long-term outcomes, such as fractures, cardiovascular disease and death, are needed, to give advice on optimal PTH levels in individual patients." (PMID 35179187, 2022). "Third, elevations in parathyroid hormone (PTH), which together with FGF23 keep serum concentrations of phosphate under tight control, have also been related to the development of cardiovascular disease." (PMID 36221075, 2022). "A lot of factors are known to be associated with lower limb arterial calcification (age, sex, previous cardiovascular disease, eGFR, NDS, PTH, inflammation and metformin)." (PMID 31168327, 2019). "PTH, parathyroid hormone; CVD, cardiovascular disease; SERM, selective estrogen receptor modulator." (PMID 35573562, 2022). "In CKD stage 5D patients, male gender, hemodialysis as modality, history of cardiovascular disease (CVD), higher age and phosphate and lower bicarbonate, PTH (both assays), residual renal function, and blood platelets all were significantly associated with higher serum sclerostin levels." (PMID 28493902, 2017).
cardiovascular disease (continued). "There are a number of clinically approved drugs, including DPP4 inhibitors and parathyroid hormone, which have the ability to enhance SDF-1/CXCR4 responsiveness and may improve the outcome of cardiovascular diseases." (PMID 26441982, 2015). "However, including either alfacalcidol or cholecalciferol treatment after transplantation did not affect hazard ratios for cardiovascular disease between quartiles of PTH." (PMID 29478201, 2018). "In another study, a positive relationship was found between PTH and PAI-1 levels in patients with PHPT without manifest cardiovascular disease." (PMID 26377856, 2016).